Y_RNA (Y RNA )
Gene: Miscellaneous RNA gene on chromosome 7 (87,218,611 to 87,218,712, reverse strand). Ensembl gene ENSG00000200397.
Homologues: Orthologues: chimpanzee Y_RNA (98% identical), macaque Y_RNA (96% identical), guinea pig Y_RNA (72% identical). Paralogues in human: Y_RNA (89% identical), RNY3 (87% identical), Y_RNA (87% identical), Y_RNA (86% identical), Y_RNA (85% identical), RNY3P1 (84% identical), Y_RNA (84% identical), RNY3P14 (83% identical), RNY3P2 (83% identical), RNY3P4 (83% identical), Y_RNA (83% identical), RNY3P16 (82% identical), and 94 more.